TERT (telomerase reverse transcriptase)
Diseases named in the same sentence as TERT in open-access papers (continued):
Sharing a sentence is not in itself a finding about the gene and the disease.
anemia (7 papers, 2008 to 2025). A reduction in the number of red blood cells, the amount of hemoglobin, and/or the volume of packed red blood cells. "A deficiency in TERT in zebrafish causes ineffective hematopoiesis accompanied by anemia, impaired specification and differentiation, hematopoietic cell apoptosis, and pancytopenia." (PMID 18846223, 2008). "This is consistent with the hypochromic anemia phenotype showing reduced o-dianisidine staining of the erythroid hemoglobin in TERT-deficient embryos." (PMID 18846223, 2008). "However, and more importantly, by expressing this mutant, the cytopenia and anemia phenotypes in the TERT-deficient zebrafish embryos were successfully rescued by restoration of the impaired differentiation of erythrocytes." (PMID 18846223, 2008). "The observation that reactivation of telomerase not only reverses anemia but also restores homeostasis in other hematopoietic cell lineages suggests a potential therapeutic approach, for example, through TERT mRNA delivery." (PMID 40244253, 2025). "Consistently, late‐generation (G3 and beyond) TERT or TERC‐deficient mice (TERT−/− and TERC−/−, respectively) are short living and show reduced fertility, early alopecia, kyphosis, anemia, and lymphopenia." (PMID 26968134, 2016). "The observation that re-activation of telomerase not only reverses anemia, but also restores homeostasis in other hematopoietic cell lineages, indicates a potential therapeutic approach, for example through TERT mRNA delivery, for bone marrow disorders that are associated with short telomeres." (PMID 26133370, 2015). "Moreover, TERT deficiency leads to the abnormal differentiation and apoptosis presumably of hematopoietic stem and/or progenitor cells, subsequently leading to the circulation of immature blood cells with anemia, by disturbing normal hematopoiesis without obvious telomere shortening." (PMID 18846223, 2008). "Bone marrow failure or spontaneous and sporadic anemia has been reported in TR-knockout mice, but not in TERT-knockout mice, although further characterizations of TERT are required in the mouse." (PMID 18846223, 2008).
Fibroadenoma (7 papers, 2017 to 2025). A benign tumor of the breast characterized by the presence of stromal and epithelial elements. "All three fibroadenomas (FAs) presented mutations in MED12, but not in TERT, whose mutation was observed in five of the 14 PTs." (PMID 38055384, 2023).
interstitial lung disease (7 papers, 2010 to 2023). A diverse group of lung diseases that affect the lung parenchyma. "The interstitial lung disease associated with the TERT mutations is characterized uniformly by dyspnea and a decreased diffusion capacity." (PMID 20502709, 2010). "Since pulmonary fibrosis is common in TERT mutation carriers, we sought to more carefully characterize the clinical interstitial lung disease phenotype." (PMID 20502709, 2010). "Interestingly, these SNPs and their corresponding annotated genes, TERC and TERT, were associated with idiopathic forms of interstitial lung disease." (PMID 37958573, 2023). "Over ninety-five percent of TERT mutation carriers with pulmonary fibrosis report an exposure to smoking and/or a fibrogenic environmental or occupational agent that may have contributed to the development of their interstitial lung disease." (PMID 20502709, 2010).
liposarcoma (7 papers, 2014 to 2023). A usually painless malignant tumor that arises from adipose tissue. "This telomere pattern is clearly different compared to tumors with telomerase reactivation, where telomere length is found almost equal.It has been shown that ALT-positive liposarcomas have a notably worse outcome, and may imply a more favorable prognosis for TERT promoter mutated liposarcomas." (PMID 24726063, 2014). "Changes in TERT-related pathways, such as gene amplifications in dedifferentiated liposarcomas (DDLPS) or FGFR3 activation in synovial sarcomas (SS), likely promote telomerase-mediated telomere maintenance." (PMID 33924498, 2021). "We observed that the two liposarcoma samples harbouring TRIO–TERT fusions display a TERT mRNA expression level ~100-fold higher than measured in samples without such a fusion." (PMID 25204415, 2014). "The genotype at the two hotspot positions of the TERT promoter of the remaining cell lines, which included two well-differentiated liposarcomas, one dedifferentiated liposarcomas, one pleomorphic liposarcoma, one liposarcoma not further subtyped, four SSs, and one fibrosarcoma, was wild type." (PMID 24726063, 2014). "Although not the focus of this study, we describe here such an example: a recurrent fusion in two dedifferentiated liposarcoma samples (2/38; 5%) encoding the non-kinase portion of TRIO, which results in upregulation of its fusion partner TERT." (PMID 25204415, 2014). "The absence of TERT promoter hotspot mutations in our series of DDLS and PLS is in line with previous studies, which largely observed deficient telomerase activity in high-grade liposarcomas." (PMID 24726063, 2014).
metastatic carcinoma (7 papers, 2017 to 2025). A carcinoma which has spread from the original site of growth to another anatomic site.
oligoastrocytoma (7 papers, 2014 to 2025). A WHO grade II tumor composed of a conspicuous mixture of two distinct neoplastic cell types morphologically resembling the tumor cells in oligodendroglioma and diffuse astrocytoma. "Furthermore, we observed a moderate frequency of TERT promoter mutations in oligoastrocytomas (31.0%, 18/58)." (PMID 24722048, 2014). "The presence of the TERT promoter and IDH1/2 mutational status may be particularly useful to refine the classification of “mixed” oligoastrocytomas." (PMID 24722048, 2014).
Parkinson disease (7 papers, 2016 to 2023). A progressive degenerative disorder of the central nervous system characterized by loss of dopamine producing neurons in the substantia nigra and the presence of Lewy bodies in the substantia nigra and locus coeruleus. "Nonetheless, TERT dysfunction may contribute to age-associated telomere shortening and neurodegenerative diseases involving the basal ganglia such as Parkinson’s and Huntington’s diseases." (PMID 33924498, 2021). "These beneficial effects of TERT protein in the brain prompted us to use two telomerase activators in old mice as well as in a mouse model of Parkinson’s disease (PD)." (PMID 33188884, 2021). "Moreover, the SMA motor neurons show enhanced expression of pluripotency-related genes (OCT4, TERT, Nanog), while gene sets required for neuronal differentiation are specifically downregulated in these cell types compared to Parkinson's disease DNs." (PMID 27536002, 2016). "For example, TERT might be able to ameliorate the effects of toxic proteins such as amyloid-β, pathological tau, and α-synuclein involved in neurodegenerative disorders such as Alzheimer’s and Parkinson’s disease possibly by activation of autophagy." (PMID 35159171, 2022).
rectal cancer (7 papers, 2019 to 2025). A primary or metastatic malignant neoplasm that affects the rectum. "In the present study, we studied patients with rectal cancer to comprehensively investigate the associations of eight common TERT SNPs with telomere length, circulating TERT mRNA in plasma, response to CRT and disease outcome." (PMID 33113831, 2020). "Single-nucleotide polymorphisms (SNPs) in the TERT gene can affect telomere length and TERT expression and have been associated with risk and/or outcome for several tumors, but very few data are available about their impact on rectal cancer." (PMID 33113831, 2020). "The aim of our study was to comprehensively investigate the associations of eight common TERT SNPs with telomere length, circulating TERT mRNA in plasma, response to neoadjuvant therapy (CRT) and disease outcome in rectal cancer patients." (PMID 33113831, 2020). "In addition, TERT mRNA levels in plasma samples of patients with rectal cancer were identified as a predictive marker of response to therapy." (PMID 34746013, 2021). "Furthermore, our previous study reported a positive correlation between TERT and telomeric zinc-finger associated protein (TZAP) expression in colon and rectal cancers using The Cancer Genome Atlas (TCGA) database." (PMID 32932803, 2020). "However, to date no data have been available on the association between TERT genetic variants and response to neoadjuvant therapy and outcome in rectal cancer patients." (PMID 33113831, 2020).
rheumatoid arthritis (7 papers, 2013 to 2025). A chronic, systemic autoimmune disorder characterized by inflammation in the synovial membranes and articular surfaces. "Using whole-exome sequencing, it was demonstrated that TERT, RTEL1, and PARN mutations occur in patients with rheumatoid arthritis-associated ILD at a 3-fold higher odds ratio than they do in a control population." (PMID 40095034, 2025). "Impaired TERT or TERC expression in T cells are involved in the pathogenesis of rheumatoid arthritis." (PMID 32366311, 2020). "In addition, telomerase insufficiency and shorter TL due to defective TERT and TERC expression were observed in naïve CD4 T cells from patients with rheumatoid arthritis, through which premature senescence of T cell subsets occurred and subsequent autoimmunity was triggered." (PMID 32366311, 2020).
acute lymphoblastic leukemia (6 papers, 2016 to 2025). Leukemia with an acute onset, characterized by the presence of lymphoblasts in the bone marrow and the peripheral blood. "We screened 105 B-cell lymphoid malignancies encompassing nine NHL subtypes and acute lymphoblastic leukemia, for TERT promoter mutations." (PMID 27792139, 2016). "In line with this, TERT inhibition via BIBR1532 was shown to increase the percentage of Annexin-V+ and Annexin-V+/Propidium Iodide+ cells, as well as increase Caspase 3 activity in a human pre-B acute lymphoblastic leukaemia cell line." (PMID 33806803, 2021).
acute promyelocytic leukemia (6 papers, 2016 to 2023). An aggressive form of acute myeloid leukemia (AML), characterized by arrest of leukocyte differentiation at the promyelocyte stage, due to a specific chromosomal translocation t(15;17) in myeloid cells. "An early study has indicated that it affects approximately half of AML (53.3%) patients, while another report indicated that TERT dysregulation is present in all acute promyelocytic leukemia (APL, AML-M3) patients in their cohort." (PMID 34440361, 2021). "The current study attempted to overcome this limitation by confirming the association between WT1 knockdown and reduced TERT expression in NB4, an acute promyelocytic leukemia cell line with known high levels of WT1 expression and HEK293 cells, a transformed human embryonic kidney cell line." (PMID 35406427, 2022). "Because other Wilms tumor cell lines with expression of WT1 were unavailable, the NB4 acute promyelocytic leukemia cell line, which demonstrates high levels of WT1 expression, was used to validate the association between shRNA knockdown of WT1 and decreased TERT expression." (PMID 35406427, 2022).
chromophobe renal cell carcinoma (6 papers, 2019 to 2025). Chromophobe renal cell carcinoma is a rare subtype of renal cell carcinoma, originating from the intercalating cells of the collecting ducts and macroscopically manifesting as a well-circumscribed, highly lobulated, solid tumor that is usually diagnosed at an early stage. "In chromophobe renal cell carcinoma, breakpoint adjacent to TERT led to an 80-fold increase in TERT expression." (PMID 37754262, 2023). "For example, our recent analysis of chromophobe renal cell carcinomas has uncovered recurrent fusions targeting the TERT promoter, with the resulting over-expression of TERT." (PMID 32631391, 2020). "Finally, in chromophobe renal cell carcinoma, chromothripsis nearly always affected chromosome 5: these samples had breakpoints immediately adjacent to TERT, increasing TERT expression by 80-fold on average compared with samples without rearrangements (P = 0.0004; Mann–Whitney U-test)." (PMID 32025007, 2020). "One of the involved genes was TERT, for which several CGI probes were highly methylated in chromophobe renal cell carcinoma (chRCC) and for which associations between SSV breakpoints and TERT expression were significant specifically for that cancer type." (PMID 31610796, 2019).
clear cell renal cell carcinoma (6 papers, 2017 to 2025). "A recent analysis of clear cell renal carcinomas has identified three additional frequently appearing mutations, which are independent of the highly recurrent TERT promoter mutations, in the TERT 5′ untranslated region." (PMID 30482235, 2018). "Interestingly, the mutation sites observed in our clear cell renal cell carcinoma data included three positions in the 5′ UTR of TERT, located 15, 24, and 29 base pairs downstream of the transcription start site." (PMID 29656891, 2018). "In chromophobe renal cancer, structural variants activating TERT are common, but we detected neither genomic rearrangements nor copy number aberrations near TERT in this cohort of clear cell renal cell carcinomas." (PMID 29656891, 2018). "To assess whether the 5′ UTR mutations were recurrent, we screened the promoter and 5′ UTR of TERT in an additional 377 samples from 94 patients with clear cell renal cell carcinoma by capillary sequencing." (PMID 29656891, 2018).
depression (6 papers, 2013 to 2024). "This pronounced decrease (between 25% to 50%) of the de novo synthesis of TERT may be partially responsible for the long-term deleterious consequences associated with depression, such as accelerated brain aging and increased susceptibility to age-related disorders." (PMID 31428223, 2019). "Our data suggested that positive stimuli trigger intensive stressful reaction of the HPA axis in TERT-deficient state, contributing to HPA axis abnormality in the pathology of depression." (PMID 36481932, 2023). "This fact confirms the important role of TERT in the treatment of depression and the potency of the antidepressant effect of the fruit." (PMID 31428223, 2019). "Accelerated aging also has been demonstrated in patients with depression characterized by a significant decrease in telomere length and expression of telomerase reverse transcriptase (TERT), the enzyme responsible for telomere maintenance." (PMID 31428223, 2019). "More recently, a strong link between levels of TERT activity in the hippocampus and depression has been demonstrated in a chronic mild stress mouse model." (PMID 23840724, 2013). "In this study, we discovered that the physiological and stress levels of GCs exhibit opposite effects while deficient and excessive GCs have similar effects on regulating NSC proliferation, adult hippocampal neurogenesis, TERT expression, learning and memory, and depression phenotype." (PMID 38421107, 2024). "Thus, our studies revealed a novel function of TERT in the pathology of depression and aggression in a brain structure-specific manner, providing direct evidence for the contribution of TERT to emotional control." (PMID 27300262, 2016). "Interestingly, chronic mild stress in mice resulted in decreased TERT levels and telomerase activity and reduced neurogenesis in hippocampus, as well as depression-like behavior." (PMID 25618407, 2015). "In animal models of depressive-like behavior, reduced TERT expression has been reported in tissues such as the liver and hippocampus, but this study is the first to show a significant decrease in three major brain regions (the hippocampus, striatum, and prefrontal cortex) involved in depression." (PMID 31428223, 2019).
emphysema (6 papers, 2015 to 2024). "The emphysema-associated TERT variants compromised telomerase catalytic activity, and mutation carriers had abnormally short telomeres." (PMID 26236580, 2015). "Mutations in TERT have also been associated with the development of emphysema and COPD." (PMID 34490311, 2021). "We conclude that catalytically active TERT prevents exhaustion of the putative CD34 + EC progenitors with age, thus protecting against capillary vessel loss and pulmonary emphysema." (PMID 38424230, 2024). "However, only TERT reduces accumulation of very short telomeres, oxidative damage, endothelial cell (ECs) senescence and senile emphysema in aged mice." (PMID 38424230, 2024). "Among patients with severe, early-onset emphysema (defined as Global Initiative for Obstructive Lung Disease Stage 3 or 4 with disease diagnosed in smokers who are younger than 65 yr), 1–2% carry a mutant TERT gene." (PMID 35532056, 2022). "sequenced the telomerase genes (TERT and TER) in COPD patients across two large cohorts (COPDgene and the Lung Health Study (LHS)) and discovered that 1% of patients with early-onset severe emphysema had deleterious TERT mutations." (PMID 33619289, 2021). "However, the mechanism by which in vivo TERT expression could prevent the occurrence of emphysema during aging remained to be elucidated." (PMID 38424230, 2024).
head and neck squamous cell carcinoma (6 papers, 2016 to 2025). A squamous cell carcinoma that arises from any of the following anatomic sites: lip and oral cavity, nasal cavity, paranasal sinuses, pharynx, larynx, and salivary glands. "Most head and neck squamous cell carcinomas show increased expression of TERT transcripts, which is associated with worse prognosis." (PMID 40278994, 2025). "We found a positive correlation between TERT expression, B and T cells in four cancer types with the strongest association in head and neck squamous cell carcinoma (HSNCC)." (PMID 36909826, 2023). "Moreover, the authors underlined those patients with head and neck squamous cell carcinoma carrying the − 124 C > T TERT promoter mutation in the tumors had more than double the risk of death and disease progression compared with patients whose tumors lacked this mutation." (PMID 40278994, 2025). "Thus, TERT promoter mutation C228T might serve as a prognostic biomarker in head and neck squamous cell carcinoma to help clinicians in the management of treatment." (PMID 32850388, 2020). "We investigated the predictive and prognostic role of TERT levels and telomere length in tissues and peripheral blood in patients with head and neck squamous cell carcinoma (HNSCC)." (PMID 31772219, 2019).
hepatocellular adenoma (6 papers, 2016 to 2024). A benign epithelial neoplasm arising from the hepatocytes. "Hepatocellular adenoma (HCA) is a kind of benign tumor; however, it has an increased risk of malignant transformation when telomerase reverse transcriptase (TERT) was activated." (PMID 33440657, 2021). "TERT promoter mutations are major genomic alterations in the step-by-step hepatocarcinogenic process, which is involved in HCC developed from chronic liver disease as well as from hepatocellular adenomas (HCA)." (PMID 26575952, 2016).